FOXC1 (forkhead box C1)
Diseases named in the same sentence as FOXC1 in open-access papers (continued):
Sharing a sentence is not in itself a finding about the gene and the disease.
cleft palate (1 paper, 2023). Cleft palate is a fissure type embryopathy that affects the soft and hard palate to varying degrees. "The only relevant HI-gene shared among the individuals with an isolated cleft palate was FOXC1, which has not specifically been related to this phenotypic feature in the literature, and a cleft palate is not typically seen in FOXC1-related ARS." (PMID 36964621, 2023).
Cognitive impairment (1 paper, 2023). Abnormal cognition is characterized by deficits in thinking, reasoning, or remembering. "USP9X was recently linked with syndromic cognitive impairment that includes hearing loss, dental defects, ventriculomegaly, Dandy–Walker malformation, skeletal anomalies (hip dysplasia), and other features showing a significant overlap with FOXC1-ARS." (PMID 37895297, 2023).
corneal disease (1 paper, 2023). "With this method, we identified that the genes associated to our “curated corneal disease list” were significantly more likely to be bound by PAX6, FOXC1, RUNX1, and FOSL2." (PMID 37856539, 2023). "To further explore the association of FOSL2 with corneal diseases, we questioned whether the target genes of FOSL2 are enriched for corneal disease genes, similar to other known LSC TFs such as PAX6, FOXC1, and p63." (PMID 37856539, 2023).
corneal ulcer (1 paper, 2021). Area of epithelial tissue loss from corneal surface; associated with inflammatory cells in the cornea and anterior chamber. "Loss of interferon regulatory factor 1 and PAX6 induced by FOXC1 dysfunction is linked to the corneal ulcer." (PMID 33414365, 2021). "Deficiency of FOXC1 and alternation in epithelial features occur in patients with corneal ulcers." (PMID 33414365, 2021). "To study the potential relationship between FOXC1 and corneal pathogenesis, we examined 21 biopsy samples from patients with corneal ulcer." (PMID 33414365, 2021). "Collectively, our results reveal a FOXC1-mediated regulatory network responsible for corneal epithelial homeostasis and provide a potential therapeutic target for corneal ulcer." (PMID 33414365, 2021). "Loss of FOXC1, IRF1, and PAX6 was observed in some regions of the corneal ulcer tissues." (PMID 33414365, 2021). "FOXC1-depleted LSCs show the activation of an epidermis-specific gene program and the repression of IRF1 and PAX6, which are pathological characteristics of the human corneal ulcer." (PMID 33414365, 2021).
diffuse large B-cell lymphoma (1 paper, 2024). "We investigate the additive prognostic value of stromal FOXC1 expression and tumor phosphorylated ERK1‐2 (pERK1‐2) expression to the established National Comprehensive Cancer Network International Prognostic Index (NCCN‐IPI), in 92 diffuse large B‐cell lymphoma (DLBCL) cases." (PMID 39404228, 2024).
Ehlers-Danlos syndrome (1 paper, 2010). The Ehlers–Danlos syndromes (EDS) are a clinically and genetically heterogeneous group of heritable connective tissue disorders (HCTDs) characterized by joint hypermobility, skin hyperextensibility, and tissue fragility. "Other possible candidates are the type V collagen genes COL5A1and COL5A2 involved in Ehlers-Danlos syndrome (EDS), fibrillin-1 gene (FBN1) responsible for Marfan syndrome, PAX6 associated with aniridia and FOXC1 associated with abnormal ocular development." (PMID 20485516, 2010).
endometrial tumor (1 paper, 2023). "There were FOXC1 up-regulation and miR-495 down-regulation in endometrial tumor tissues compared with healthy tissue." (PMID 37689738, 2023). "FOXC1 inhibited the endometrial tumor cell proliferation and migration." (PMID 37689738, 2023). "There was a negative correlation among miR-495 and FOXC1 and inhibition of endometrial tumor progression." (PMID 37689738, 2023).
Failure to thrive (1 paper, 2023). Failure to thrive (FTT) refers to a child whose physical growth is substantially below the norm. "The family was counseled that FOXC1 can be associated with hearing loss, brain anomalies, hypotonia, and failure to thrive in addition to ocular anomalies that would require continuous monitoring." (PMID 36980998, 2023).
gestational diabetes (1 paper, 2023). Carbohydrate intolerance first diagnosed during pregnancy. "Two of these – namely DDX39A and LMBR1L – potentially contribute to immune responses and inflammation, whereas FOXP1 and FOXC1 have been linked to preeclampsia and gestational diabetes, respectively." (PMID 36840948, 2023).
glomerular disease (1 paper, 2023). "Many of the transcription factors have previously been shown to play a role in podocyte injury and glomerular disease, such as MAFB, TCF21, DACH1 and the recently reported FOXC1." (PMID 37681897, 2023).
Harlequin ichthyosis (1 paper, 2016). Harlequin ichthyosis (HI) is the most severe variant of autosomal recessive congenital ichthyosis (ARCI; see this term). "ABCA12, a gene with function in keratinocyte lamellar body lipid transportation and its loss-of-function mutations are associated with harlequin ichthyosis, was also significantly reduced in FOXC1-silenced KC." (PMID 27907090, 2016).
Hereditary breast cancer (1 paper, 2019). Breast carcinoma that has developed in relatives of patients with history of breast carcinoma. "Among the highest-scoring genes detected using the proposed method, it is suspected that STARD3, PGAP3, ORMDL3, PSMD3 and HAPLN3 are the biomarkers of the HER2 + subtype, thus indicating that FOXC1 can identify basal-like subtypes in hereditary breast cancer cohorts." (PMID 31296201, 2019).
infarction (1 paper, 2020). A localised pathological necrosis of tissue resulting from obstruction of the blood supply usually by a thrombus, an embolus, or vascular torsion. "ELISA showed that FoxC1 expression gradually increased over time, peaked at 15 days after infarction, and then decreased." (PMID 32963702, 2020).
Insulin resistance (1 paper, 2025). Increased resistance towards insulin, that is, diminished effectiveness of insulin in reducing blood glucose levels. "FOXC1 contributes to insulin resistance by driving chronic inflammation and promotes cancer progression by enhancing cell proliferation, survival, invasion, and a pro-tumorigenic microenvironment." (PMID 40127075, 2025).
invasive carcinoma (1 paper, 2010). A carcinoma that is not confined to the epithelium, and has spread to the surrounding stroma. "Further studies are needed to investigate the functional consequence of this increase of DNA methylation and the potential role of FOXC1 in the progression from DCIS to invasive carcinoma." (PMID 20056007, 2010).
ischemic disease (1 paper, 2020). Lack of blood supply to an area of the body, resulting in impairment of tissue oxygenation. "In this manner, the niche that is enriched with FoxC1 and angiogenesis may serve as an optimal host microenvironment for transplanted stem cells post-MI, and investigation of such adaptive mechanisms should provide a potential therapeutic target for the future treatment of ischemic diseases." (PMID 32963702, 2020).
keloid (1 paper, 2023). An irregularly shaped, elevated mark on the skin caused by deposits of excessive amounts of collagen during wound healing. "In our present study, we screened bone/cartilage-related genes (COMP, ASPN, COL5A2, COL10A1, and COL11A1), transcription factor (FOXC1), and miRNA (miR-335-5p) in major fibrotic skin diseases including keloid and SSc." (PMID 37082197, 2023). "The FOXC1 and miR-335-5p networks may collaborate in the keloid and SSc processes." (PMID 37082197, 2023).
laryngeal carcinoma (1 paper, 2022). Carcinoma that arises from the laryngeal epithelium. "miR-204-5p was also down-modulated in N+ LSCC samples and in T3–T4 stages; functional analysis showed that miR-204-5p can attenuate cell proliferation, migration, invasion, and EMT processes in laryngeal cancer cells by targeting Forkhead box C1 (FOXC1)." (PMID 35406495, 2022).
mantle cell lymphoma (1 paper, 2023). Mantle cell lymphoma is a rare form of malignant non-Hodgkin lymphoma affecting B lymphocytes in the lymph nodes in a region called the ``mantle zone''. "For example, FOXC1 and FOXL2, which are mutated in people affected by Dandy-Walker and regulate cerebellum development, are hypermethylated in mantle cell lymphomas with increased levels of G9A." (PMID 37470706, 2023).
metastatic cancers (1 paper, 2021). A carcinoma which has spread from the original site of growth to another anatomic site. "By accurately identifying those patients with FOXC1+ pro-metastatic cancer who are at greatest risk, such a test serves to refine and improve resource utilization, to optimize delivery of life-saving chemotherapy and targeted therapy to the patients who need it the most." (PMID 34540690, 2021). "In this review, we also highlight several potential targeted therapeutic strategies, based on utilizing already available FDA-approved oral anticancer drugs, that may help achieve improved clinical outcomes for patients diagnosed with FOXC1-overexpressing pro-metastatic cancers." (PMID 34540690, 2021). "Pharmacologic targeting of the IL-8/FOXC1/CXCR1 and FOXC1/NFκB/IL-6 positive feedback loops hold promise for deriving clinical therapeutic benefit in FOXC1+ pro-metastatic cancers." (PMID 34540690, 2021).
mitral valve regurgitation (1 paper, 2023). "Genetic evidence indicates mutations of the transcription factor FOXC1 are associated with MV defects, including mitral valve regurgitation." (PMID 37693499, 2023).
mixed tumours (1 paper, 2010). "Significantly lower levels of FOXC1 methylation were observed in DCIS compared to invasive and mixed tumours (P = 0.007, and P = 0.001, respectively)." (PMID 20056007, 2010).
Myocardial fibrosis (1 paper, 2024). "There is evidence that FOXC1 can promote angiogenesis in the ischemic injury area, and prevent the subsequent decline in cardiac function by reducing myocardial fibrosis." (PMID 39086489, 2024).
neurofibroma (1 paper, 2024). An intraneural or extraneural neoplasm arising from nerve tissues and neural sheaths. "Additionally, transcription factors such as FOXC1, which has been associated with the development of multiple tumors, TBX3, associated with Ulna-Mamma Syndrome, and TEAD1, linked to Neurofibroma and Spindle Cell Rhabdomyosarcoma, could be considered targets for drug repositioning." (PMID 38673810, 2024).
neuropathy (1 paper, 2019). A disorder affecting the nervous system that manifests with pain, tingling, numbness, and/or muscle weakness. "A GWAS on oxaliplatin-induced neuropathy implicated genes relating to nerve development and neuron extension (FOXC1 and ITGA1) and pain signaling neurotransmitters (TAC1)." (PMID 30909387, 2019).
Nystagmus (1 paper, 2016). Rhythmic, involuntary oscillations of one or both eyes related to abnormality in fixation, conjugate gaze, or vestibular mechanisms. "Thus hemizygous expression of FOXC1 and FOXF2 may explain the corneal abnormalities, iridogoniodysgenesis and nystagmus observed in the patient." (PMID 27103944, 2016).
osteoporosis (1 paper, 2023). A condition of reduced bone mass, with decreased cortical thickness and a decrease in the number and size of the trabeculae of cancellous bone (but normal chemical composition), resulting in increased fracture incidence. "Because we saw a decrease in FOXC1 in ovariectomized mice, we sought to determine if there is a decrease in FOXC1 in osteoporosis." (PMID 37754840, 2023).
polydactyly (1 paper, 2019). A disease characterized by the presence of polydactyly, including syndromic and non-syndromic forms. "A recent study showed that mutations in the FOXC1 gene in humans cause, in addition to ASD, systemic conditions similar to those found in ciliopathic patients including polydactyly." (PMID 31845891, 2019).
primary lymphedema (1 paper, 2020). A congenital condition that results in swelling in the arms or legs, and can occur during adolescence or adulthood. "Our findings elucidate a key contribution of FOXC1, complementary to FOXC2, in regulating lymphatic valve maturation and maintenance and provide additional insight into disease processes potentially associated with primary lymphedema." (PMID 32510325, 2020).
prostate tumours (1 paper, 2009). "The genes with the greatest fold changes in the datasets, FOXC1 and VAX1, will require future validation in a larger series of prostate tumours." (PMID 19283074, 2009).
syngnathia (1 paper, 2013). "Together our data demonstrates that Foxc1 – Fgf8 signaling regulates mammalian jaw patterning and provides a mechanistic basis for the pathogenesis of syngnathia." (PMID 24385915, 2013). "In this study we present the first genetic model, a targeted deletion of Foxc1, with which to further understand the etiology and pathogenesis of human syngnathia." (PMID 24385915, 2013). "Thus Fgf8 may be required to maintain proper levels of Foxc1 in the PA1 mesenchyme and conversely Foxc1 may be required to maintain proper levels of Fgf8 in the PA1 oral ectoderm forming a feedback loop critical for jaw development and in the pathogenesis of syngnathia and TMJ agenesis." (PMID 24385915, 2013).
synovial sarcoma (1 paper, 2006). "It was recently reported that FOXC1 was associated with tumours originating from the mesenchyme including synovial sarcomas." (PMID 17134502, 2006).
thymoma (1 paper, 2024). A neoplasm arising from the epithelial cells of the thymus. "In summary, the loss in the 6q25.2–25.3 region, housing the FOXC1 tumor suppressor gene located at 6p25.3, is evident in all TET subtypes except for Type B1 thymomas; although, the limited number of B1 thymomas in the analyzed cases may have influenced this outcome." (PMID 38338833, 2024).
thyroid cancer (1 paper, 2020). "One prior study found that FOXC1 is strongly associated with thyroid cancers." (PMID 32093341, 2020).
ZIKV infection (1 paper, 2020). "According to previous studies, FOXC1 is required for normal cerebellar development and impairment of FOXC1 function contributes to the development of Dandy–Walker syndrome, which is a brain malformation associated with ZIKV infection." (PMID 33121145, 2020). "Since FOXC1 was downregulated in lt-NES® cells following ZIKV infection, it could be a contributing factor to the development of congenital ZIKV syndrome." (PMID 33121145, 2020). "However, further studies should be performed to investigate if FOXC1 is repressed due to the upregulation of miR-4792 in lt-NES® cells upon ZIKV infection." (PMID 33121145, 2020).
tumor (131 papers, 2006 to 2026). "Xu and colleagues reported that the TGF-β-associated pathway, through the regulation of FOXC1, affects tumour EMT, thereby promoting MVI." (PMID 39944086, 2025). "FOXC1 is a crucial transcriptional regulator of potential proteins that are associated with carcinomas and regulated genes associated with tumor." (PMID 38717954, 2024). "The literature has indicated that abnormal FOXC1 expression patterns are associated with tumor progression and poor prognosis." (PMID 39430239, 2024). "FOXC1, on the other hand, promotes tumor growth and metastasis by regulating genes associated with epithelial–mesenchymal transition and angiogenesis, contributing to poor clinical outcomes." (PMID 39656775, 2024). "Both high FOXC1 stroma group and high pERK1‐2 tumor group were significantly associated with shorter progression‐free survival (PFS) and overall survival (OS) compared with low group (p = 0.015, 0.034 and p = 0.025, 0.025 each respectively)." (PMID 39404228, 2024). "In conclusion, the expression of stromal FOXC1 and tumor pERK1/2 was associated with both prognosis and underlying tumor biology, reflecting the tumor microenvironment in DLBCL." (PMID 39404228, 2024). "In this study, we first establish that, although phenotypically FOXC1 affects the major tumour-associated properties in TNBC, only 26 genes are differentially expressed upon loss of FOXC1 across four TNBC cell lines with varying levels of FOXC1 expression." (PMID 39171293, 2024). "Multivariable Cox proportional hazards model of stromal cell FOXC1 and tumor cell pERK1‐2 expression, NCCN‐IPI risk group, cell of origin, and MYC/BCL2 double expression in DLBCL patients (n = 92)." (PMID 39404228, 2024). "FOXC1 has been linked to cartilage differentiation, vascular development, tumor development, and metastasis." (PMID 37082197, 2023). "FOXC1 overexpression has been associated with more aggressive tumour behaviour and poorer prognosis." (PMID 35267409, 2022). "A study reported that various tumor-associated genes are regulated by FOXC1 and maintain several cancer-related pathways." (PMID 35632527, 2022). "We explored how the loss of FOXC1 would affect tumor growth in vivo and injected FOXC1-deficient cells into nude mice to establish xenograft models." (PMID 35096062, 2022). "FOXC1 is also associated with the IL-8 signaling pathway and the transactivation of genes responsible for tumour angiogenesis and metastasis, CXCR2 and CCL2." (PMID 29487724, 2018). "Accumulating evidence suggests that cancer stem cells (CSCs) play a critical role in tumor initiation, progression and therapy, and recent studies have indicated that Forkhead box C1 (FOXC1) is strongly associated with CSCs." (PMID 30189871, 2018). "The underlying mechanism may be that FOXC1 is involved in tumor development and metastasis, including cell proliferation, epithelial-mesenchymal transition, and angiogenesis." (PMID 41333181, 2025). "Notably, individuals presenting with a FOXC1 deficiency display an expedited rate of tumor progression, as well as a markedly abbreviated disease-related survival span." (PMID 37849766, 2023). "To further confirm whether proliferation was affected, we used Ki67 to stain the tumor sections and found few Ki67+-stained cells in FOXC1-deficient tumors, indicating that the loss of FOXC1 inhibits cell proliferation in these xenograft tumor models." (PMID 35096062, 2022). "Maheswaran and colleagues had found that mesenchymal cells expressing known EMT regulators, including TGF-β pathway components and the FOXC1 transcription factor, were highly enriched in circulating tumor cells (CTCs) and these mesenchymal CTCs were associated with disease progression." (PMID 34540690, 2021).